RREB1 (ras responsive element binding protein 1)
Diseases named in the same sentence as RREB1 in open-access papers (continued):
Sharing a sentence is not in itself a finding about the gene and the disease.
plasma cell tumors (1 paper, 2008). "Rreb1 binds and represses expression of the p16(Ink4a) promoter, and the development of pristane-induced plasma cell tumors in Balb/C mice is attributable to a polymorphism in this Rreb1 binding site." (PMID 18485879, 2008).
renal fibrosis (1 paper, 2025). A final common manifestation of a wide variety of chronic kidney diseases characterized by glomerulosclerosis and tubulointerstitial fibrosis. "In our study, we demonstrated that HRAS activated RREB1, enhancing SMAD2/3 association with Snai1 and Has2cis-regulatory regions during renal fibrosis." (PMID 39913299, 2025).
Rett syndrome (1 paper, 2014). A severe neurodevelopmental disorder affecting the central nervous system. "Of these, binding sites for the three transcription factors RREB1, FOXP1 and NFY were found in all three genes, suggesting that the three genes implicated in Rett syndrome may be regulated by the same TFs in humans." (PMID 25539566, 2014).
cancer (28 papers, 2008 to 2025). A tumor composed of atypical neoplastic, often pleomorphic cells that invade other tissues. "It is reported that RREB1 has been implicated in the regulation of tumorigenesis and progression in a number of cancers." (PMID 36635261, 2023). "For example, Tff3, Hpse, Slit1, Spon1, Spock1, and Spock3 are associated with increased cancer cell invasion and were upregulated in Rreb1-/-, and Selenbp1 and Serpin6b are tumor suppressor genes that were downregulated." (PMID 33929320, 2021). "The transcription factor Rreb1 is necessary for invertebrate development and is implicated in cancer, suggesting that it plays critical contextual organismal functions." (PMID 33929320, 2021). "In conclusion, RREB1 is a promising diagnostic biomarker or new drug target for cancers and metabolic diseases." (PMID 32210733, 2020). "It was reported that RAS signaling caused repression of the miR-143/145 by activating Ras-responsive element-binding protein 1 (RREB1) in many cancers." (PMID 32102538, 2020). "Thus, disentangling the function of Rreb1 in development should shed light on its role in cancer and other diseases involving loss of epithelial integrity." (PMID 33929320, 2021). "Together these data suggest that the embryonic role of Rreb1 may be functionally linked to its role in cancer." (PMID 33929320, 2021). "Rreb1 has been implicated in cancer and Noonan-like RASopathies." (PMID 33929320, 2021). "In sum, we describe phenotypes and cell behaviors in Rreb1 mutant mouse embryos reminiscent of those observed during cancer cell invasion, including loss of epithelial architecture, aberrant basement membrane breakdown, ECM remodeling, and ectopic exit of cells from an epithelium." (PMID 33929320, 2021). "Thus, loss of Rreb1 in the mouse embryo caused epiblast epithelial cells to cross the basement membrane underlying the epiblast epithelium, reminiscent of the invasive cell behaviors observed in cancer metastasis." (PMID 33929320, 2021). "Moreover, mutation or altered expression of Rreb1 has been linked to leukemia, melanoma, thyroid, and prostate cancers, as well as pancreatic and colorectal cancer metastasis (Cancer Genome Atlas Research Network." (PMID 33929320, 2021). "Blocking RREB1 disrupts this process, preventing metastasis and presenting RREB1 as a potential target for cancer therapy." (PMID 39682234, 2024). "The RAS-responsive element binding protein 1 (RREB1) leads to the transcriptional repression of the miRNA-143/145 cluster, and miRNA-143/145, in turn, represses RREB1 expression, creating a cancer-promoting feedback loop of RAS signalling." (PMID 39001340, 2024). "As previously explained, an imbalance of RREB1 function plays a role in the development of various cancers and other diseases." (PMID 38928466, 2024). "It has been shown that RREB1 is a crucial partner of TGF-β pathways in promoting cancer progression." (PMID 36635261, 2023). "We previously showed that, in a cancer model, Rreb1 directly binds to the regulatory region of Snai1 in cooperation with TGF-β activated SMAD transcription factors to induce the expression of SNAIL, which drives EMT." (PMID 33929320, 2021). "The cell behaviors observed in Rreb1-/- embryos and chimeras are similar to those observed in cancer." (PMID 33929320, 2021). "RREB1 is an oncogenic TF that suppresses miR143/145 expression to establish Ras/ERK oncogenic signaling in several cancers." (PMID 31822798, 2020). "In the future, with the deep research on RREB1, it will be possible to provide new potential therapeutic targets for cancers and metabolic diseases." (PMID 32210733, 2020). "In general, more and more evidences show RREB1 is important for cancer occurrence and other diseases." (PMID 32210733, 2020). "Mitogen-activated protein kinase (MAPK) signaling is deregulated in most cancers and downregulates miR-145 expression via Ras-responsive element-binding protein (RREB1), which directly binds and suppresses miR-145 promoter." (PMID 25333257, 2014).
cancer (continued). "RREB1 is expressed in developing tissues and cancer where it acts downstream of Ras and MAPK signaling Twist1 is required for K-Ras mediated progression of lung tumors, supporting a role for RREB1 in this regulatory interaction." (PMID 25262113, 2014). "Cross species comparative analysis with aCGH data of human cancer cell lines revealed known and candidate oncogenes (Mmp13, Slamf6, and Rreb1) and tumor suppressors (Wwox and Arfrp2)." (PMID 18485879, 2008). "RREB1 also plays an important role in Ras signaling, leading to the development of several cancers." (PMID 34316701, 2021). "Therefore, targeting RREB1 with small molecule compounds will be a promising way for cancer therapy." (PMID 32210733, 2020). "Our review focuses on RREB1-involved signaling pathways, the target genes regulated by RREB1, the role of RREB1 in cancer and disease development and the clinical application of RREB1, which is helpful for comprehensive understanding RREB1 multiple functions in physiological and pathological states." (PMID 32210733, 2020). "We have summarized the target genes of RREB1 and discussed RREB1 roles in the cancer development." (PMID 32210733, 2020). "However, it should be noted that the specificity of RREB1 expression was overall poor, as most cancer types had comparable mRNA levels." (PMID 33080033, 2020). "The indirect evidences indicate that RREB1-mediated immune mechanism may be involved in the regulation of cancer development." (PMID 32210733, 2020). "Motifs 5 and 7 match the Arabidopsis thaliana transcription factor trp_AtMYB-84_M00970 (e-value = 1.35–7.08e-10) and the Ras responsive element binding protein-1 (RREB-1) (e-value = 5.09e-9–1.38e-6), respectively, the latter of which regulates immunity and cancer-related gene expression in humans." (PMID 23209765, 2012). "We identify several novel candidate cancer genes including Rreb1, Mmp13 and Arfrp2 (Arl15)." (PMID 18485879, 2008). "Thus, Rreb1-/- cells might perform a role comparable to leader cells in cancer metastasis, remodeling the ECM to permit migration of wild-type neighbors." (PMID 33929320, 2021). "However, whether RREB1-mediated immunomodulatory is involved in cancer development is still to be investigated." (PMID 32210733, 2020). "Eight of these nine were consistently associated with clinical phenotypes, of which three exhibited statistical significance in both differential analyses between cancer and adjacent tissues, and survival analyses (FAM83E pS351, RREB1 pS161, and TNS2 pS830)." (PMID 39793886, 2025). "RREB1 is a well-known RAS transcription effector and mediates TGF-β-induced epithelial-to-mesenchymal transitions (EMTs) in human cancers." (PMID 37596700, 2023). "During EMT in cancer tissue, RAS-responsive element binding protein 1 (RREB1) directly cooperates with TGF-β-activated SMAD transcription factors." (PMID 35814409, 2022). "SMADs expressing RREB1 directly control the expression of mesoderm genes and EMT transcription factors in pluripotent progenitor cells, as well as the expression of EMT transcription factors and fibrous factors in cancer cells." (PMID 37598126, 2023). "Moreover, as the effector of RAS signaling, RREB1 was reported to contribute to EMT, proliferation and invasiveness in multiple human cancers." (PMID 37596700, 2023). "The universality of the TGF-SMAD- RREB1 mechanism also offers the door for a fuller understanding of the role of TGF-β in organ fibrosis and cancer pathogenesis and provides a consistent framework for examining EMT throughout the course of development and regeneration." (PMID 37598126, 2023).
cancer (continued). "During EMT, TGF-β triggers two simultaneous effects, increased cancer cell plasticity via RREB1 and SMAD and inhibition of adipogenesis by the non-canonical MEK-ERK pathway." (PMID 35814409, 2022). "Also, 60% of cancers negative for KRAS mutation had a mutation in the RAS-MAPK signaling pathway gene, such as RREB1 (ras responsive element binding protein 1)." (PMID 40981070, 2025).
tumor (17 papers, 2008 to 2025). "RREB1::MRTFB fusion-positive extra-glossal mesenchymal neoplasm is a recently recognized tumor so far mostly described in the head and neck area and in the mediastinum." (PMID 41449216, 2025). "The next most recurrently mutated driver gene was the transcription factor RAS responsive element binding protein-1 (RREB1; n = 86/197), with many tumours having multiple mutations (n = 47/86)." (PMID 41419736, 2025). "Recently, neoplasms carrying the RREB1::MRTFB fusion and showing a variable morphological and immunophenotypic overlap with glossal ECT have been reported from diverse head and neck as well as from non-head and neck sites." (PMID 38491228, 2024). "This tumor is characterized in most cases by a RREB1::MRTFB fusion, while there is EWSR1 gene rearrangement in a smaller subset of cases." (PMID 38491228, 2024). "Gross pathological examination showed that the size of the tumor mass was about 14 × 10 × 6 cm.Mutations were observed in ENPEP (4q25), ZCCHC11, RREB1 (6p24.3), CKAP4 (12q23.3), and other genes were detected by whole exome sequencing." (PMID 36805679, 2023). "In the same mouse model, TGF-β and RAS-MAPK signals acted jointly through SMAD family members (SMADs) and Ras responsive element binding protein 1 (RREB1) transcription factors trigger EMT to promote tumor progression." (PMID 36823234, 2023). "Because RREB1 plays an important role in tumorigenesis, RREB1 is a good marker for tumor diagnosis, prognosis prediction and management of patients." (PMID 32210733, 2020). "Tumours with RREB1 mutations predominantly (but not exclusively) also had NOTCH1 mutations (n = 71/86)." (PMID 41419736, 2025). "Additionally, SLC39A3 and SLC41A1 have been reported to suppress tumor growth by downregulating Ras-responsive element-binding protein 1 (RREB1) and suppressing the activation of Akt/mTOR signaling, respectively." (PMID 38534987, 2024). "In addition, the combination of circNCAPG overexpression and RREB1 knockdown significantly decreased circNCAPG overexpression tumor volumes." (PMID 36635261, 2023). "However, the role of RREB1 is complex and can demonstrate both oncogenic and tumor suppressive properties in different systems." (PMID 27835861, 2017). "Moreover, anti-tumor immunity/immune tolerance was also regulated by RREB1 through targeting HLA-G." (PMID 32210733, 2020). "We suspected that RREB1 Q392* might be a hotspot loss-of-function mutation and the gene itself a TSG in BCa, given the fact that samples with the RREB1 Q392* mutation displayed significantly lower levels of expression for this gene than non-mutated tumours." (PMID 32988402, 2020). "RAS-responsive element-binding protein 1 (RREB1) leads to the transcriptional repression of the miR-143/145 cluster, and in turn, miR-143/145 suppresses expression of RREB1, forming a tumor-promoting feedback circuit of RAS signaling." (PMID 32138313, 2020). "However, temporal expression of RREB1 may be important for tumor development and maintenance." (PMID 27835861, 2017). "For example, IC1 – IC3 and IC6 overlapped with molecular subtype A (standardised residuals 2:4 each), which is characterised by a high proportion of mutations in driver genes such as NOTCH1 and RREB1 (with or without BICRA and MIDEAS mutations) and was found mostly in benign dMMR tumours." (PMID 41419736, 2025). "We also predicted some driver mutations in genes that were not reported to display oncogenic or tumour suppressive properties in BCa, such as AHR Q383H and RREB1 Q392*." (PMID 32988402, 2020).
infection (2 papers, 2022 to 2023). The state of being infected such as from the introduction of a foreign agent such as serum, vaccine, antigenic substance or organism. "Furthermore, gga-miR-155 and gga-miR-27b-3p were regulated by RREB1 target genes at 4 days post-infection." (PMID 38288128, 2023). "The motifs discovered were then compared with known TF binding motifs, revealing enrichment at loci opening chromatin during infection for the AP-1 (JUN-FOS), RELA (an NFκB family member) and RREB1 TFs." (PMID 36178892, 2022).
metabolic disease (2 papers, 2020 to 2021). A congenital disorder (due to inherited enzyme abnormality) or acquired (due to failure of a metabolically important organ) disorder resulting from an abnormal metabolic process. "RREB1 is widely involved in the development of tumorigenesis and metabolic diseases by regulating various target genes." (PMID 32210733, 2020).
RREB1 also shares sentences with these, for which no sentence is quoted: hepatocellular carcinoma (3 papers); breast carcinoma (2); cutaneous melanoma (2); age-related macular degeneration (1); asthma (1); autoimmune disease (1); colorectal tumor (1); coronary artery disease (1); Costello syndrome (1); depression (1); diabetic nephropathy (1); Fanconi anemia (1); Granuloma (1); insomnia (1); Lipedema (1); lung fibrosis (1); mismatch repair deficiency (1); neurological diseases (1); nonsmall cell lung cancer (1); pancreatic adenocarcinoma (1); pancreatic ductal adenocarcinoma (1); pituitary adenomas (1); pregnancy disorder (1); psoriasis (1); sarcoidosis (1); sarcoma (1); Spitz nevi (1); superficial spreading melanoma (1); Tetralogy of Fallot (1); theileriasis (1).